RNU6-778P (RNA, U6 small nuclear 778, pseudogene)
Gene: Small nuclear RNA gene on chromosome 1 (199,888,159 to 199,888,261, forward strand). Ensembl gene ENSG00000200139.
Homologues: Orthologues: chimpanzee U6 (100% identical), macaque U6 (92% identical), pig U6 (81% identical), guinea pig U6 (78% identical). Paralogues in human: RNU6-11P (86% identical), RNU6-37P (86% identical), RNU6-393P (86% identical), RNU6-1083P (85% identical), RNU6-1145P (85% identical), RNU6-1175P (85% identical), RNU6-1209P (85% identical), RNU6-16P (85% identical), RNU6-28P (85% identical), RNU6-1 (84% identical), RNU6-1251P (84% identical), RNU6-15P (84% identical), and 1286 more.